CDK1 (cyclin dependent kinase 1)
Diseases named in the same sentence as CDK1 in open-access papers (continued):
Sharing a sentence is not in itself a finding about the gene and the disease.
pulmonary fibrosis (3 papers, 2022 to 2025). Chronic progressive interstitial lung disorder characterized by the replacement of the lung tissue by connective tissue, leading to progressive dyspnea, respiratory failure, or right heart failure. "A comprehensive analysis of lung samples from 585 patients with idiopathic pulmonary fibrosis (IPF) revealed that CDK1, a cell cycle-dependent kinase, is a key regulator in fibrosis." (PMID 38343538, 2024). "By analyzing the target interaction network VCAM1,RELA,CDK2,JUN,CDK1,HSP90AA1,NOS2, SOD1,CASP3,AHSA1, PTGER3 are at the core of the network, which can be regarded as the key targets of Astragalus polysaccharides in treating pulmonary fibrosis." (PMID 35370663, 2022).
small cell lung carcinoma (3 papers, 2020 to 2024). Small cell lung cancer (SCLC) is a highly aggressive malignant neoplasm, accounting for 10-15% of lung cancer cases, characterized byrapid growth, and early metastasis.
Stroke (3 papers, 2018 to 2023). Sudden impairment of blood flow to a part of the brain due to occlusion or rupture of an artery to the brain. "This accumulation of inactive cyclin–CDK1 complexes provides a simple means of reducing the complex adhesion maintenance activity of CDK1 at a stroke and acts as a temporal switch to trigger loss of adhesion complexes coordinated with entry into G2." (PMID 29930204, 2018). "Collectively, these data suggest that Cdk1 is a key mediator of neuronal loss following stroke." (PMID 29581894, 2018). "According to studies, CDK1 may contribute to stroke through an oxidative mode of damage and may also be a potential biomarker for NSCLC." (PMID 37265472, 2023). "Taken together, the combination of this peptide with a specific Cdk1 inhibitor—such as RO-3366—may lead to an efficient neuroprotection and stroke recovery." (PMID 29581894, 2018). "However, the role of Cdk1 and its effect on stroke outcomes are not known." (PMID 29581894, 2018).
adenomyosis (2 papers, 2020 to 2022). The growth of endometrial tissue inside the muscular wall of the uterine corpus. "We found that mifepristone causes cell cycle arrest through inhibiting CDK1 and CDK2 expressions and induces cell apoptosis via the mitochondria‐dependent signalling pathway in endometrial epithelial cells and stromal cells of adenomyosis." (PMID 31814282, 2020).
ameloblastoma (2 papers, 2016 to 2022). The most common odontogenic tumor, arising from the epithelial component of the embryonic tooth and usually affecting the molar-ramus region of the mandible or maxilla. "Our literature search revealed a single study where CDK1 expression was reported in human ameloblastoma AM-1 cells." (PMID 28357197, 2016). "However, our multivariate analysis found that CDK1 expression was significantly downregulated in ameloblastoma tissue compared to the corresponding healthy controls (FC = 0.33; P value = 0.0099)." (PMID 36160115, 2022).
autoimmune disease (2 papers, 2017 to 2025). A disorder resulting from loss of function or tissue destruction of an organ or multiple organs, arising from humoral or cellular immune responses of the individual to their own tissue constituents. "Determining the exact substrates of CDK1 involved in this process may help to develop therapies for autoimmune diseases and chronic inflammatory diseases caused by neutrophils." (PMID 41040318, 2025). "Of them 12 are associated with other autoimmune diseases than SLE, whereas three genes (ZNF804A, CDK1, and MANF) have not previously been associated with autoimmunity." (PMID 28740209, 2017).
bowel cancers (2 papers, 2021 to 2024). "Unlike the aberrant expression of CDK-1 in stage-2 colon and rectum adenocarcinoma being associated with a higher risk of metastasis, mutations in the catalytic subunit of CDK-4 gene has also been reported to be common and its abnormal expression has been uncovered in over 90 % of all bowel cancers." (PMID 33732631, 2021).
brain ischemia (2 papers, 2018 to 2021). Diminished or absent blood supply to the brain caused by obstruction (thrombosis or embolism) of an artery resulting in neurologic damage. "CDK1 is associated with macrophage proliferation in vivo after brain ischemia." (PMID 33429982, 2021). "After brain ischemia, CDK1 in vitro and CDK5 in vitro and in vivo are upregulated and associated with neuronal apoptosis." (PMID 33429982, 2021). "We therefore examined the role of Cdk1 in neuronal cell death following cerebral ischemia, using both in vitro and in vivo genetic and pharmacological approaches." (PMID 29581894, 2018). "To confirm these results, we investigated whether pharmacological inhibition of Cdk1 also ameliorates cerebral ischemia–reperfusion injury." (PMID 29581894, 2018).
chronic kidney disease (2 papers, 2015 to 2024). Impairment of the renal function secondary to chronic kidney damage persisting for three or more months. "Recent studies reported that the expression levels of cyclin B2 and CDK1 were increased in proliferating tubular epithelial cells from rats with chronic renal failure, and that G2/M arrest of proximal tubular epithelial cells was involved in kidney fibrogenesis." (PMID 26317775, 2015).
cutaneous melanoma (2 papers, 2022). A primary melanoma arising from atypical melanocytes in the skin. "Mutation and deep deletion were observed in cutaneous melanoma, which had the second highest frequency of CDK1 genetic alterations (3.15%)." (PMID 35681641, 2022).
Ewing sarcoma (2 papers, 2022 to 2026). A small round cell tumor that lacks morphologic, immunohistochemical, and electron microscopic evidence of neuroectodermal differentiation. "Collectively, these findings define a unique CDK1- and caspase-dependent apoptotic pathway in response to replication stress and offer new insights into the molecular basis of this therapeutic vulnerability in Ewing sarcoma." (PMID 42270776, 2026).
Hepatic steatosis (2 papers, 2020 to 2026). Steatosis is a term used to denote lipid accumulation within hepatocytes. "Similarly, aged Cdk1 cKO mice develop hepatic steatosis with an accumulation of TGs, in contrast to young Cdk1 cKO mice which have reduced amounts of TGs instead." (PMID 33345777, 2020). "This suggests the possibility that non-CDK1-dependent senescent pathways, such as the senescence-associated secretory phenotype (SASP), may contribute to hepatic steatosis upon aging." (PMID 33345777, 2020). "Aged Cdk1 cKO mice develop hepatic steatosis progressing to steatohepatitis." (PMID 33345777, 2020). "In addition to hepatic steatosis, we also observed increased fibrosis in the livers of aged Cdk1 cKO mice." (PMID 33345777, 2020). "Hence, it will be interesting to explore whether the deletion of CDK1 in the non-parenchymal cells also induces liver steatosis." (PMID 33345777, 2020).
Hyperinsulinemia (2 papers, 2020 to 2025). An increased concentration of insulin in the blood. "In conclusion, our findings suggest that upon loss of CDK1, hepatocytes become defective in FAO oxidation, causing excessive FFAs to promote hyperinsulinemia." (PMID 33345777, 2020). "A rescue of mitochondrial FAO in Cdk1 cKO mice would help us delineate the relative contribution of the FFA-hyperinsulinemia pathway to the phenotypes seen in the aged mice." (PMID 33345777, 2020). "Notably, hyperinsulinemia was sustained upon aging in Cdk1 cKO mice given that this is a constitutive knockout model." (PMID 33345777, 2020). "Correspondingly, our data suggest that attenuated CDK1 function might contribute to age-related hyperinsulinemia." (PMID 33345777, 2020). "It has been reported that hepatocyte-specific knockout of CDK1 reduces hepatic triglyceride (TG) levels, but simultaneously impairs fatty acid oxidation (FAO) in hepatocytes, leading to excessive free fatty acids (FFA) that promote hyperinsulinemia." (PMID 40722708, 2025).
leiomyoma (2 papers, 2017 to 2025). A well-circumscribed benign smooth muscle neoplasm characterized by the presence of spindle cells with cigar-shaped nuclei, interlacing fascicles, and a whorled pattern. "For CDK1, only strong (++) staining was classified as positive to avoid false positives, as moderate staining was observed in 25% (16/65) of leiomyomas." (PMID 41162745, 2025). "Expression of cyclin E and cyclin-dependent kinase 1 was significantly increased in leiomyoma cells by hCG treatment." (PMID 28930160, 2017).
liver cirrhosis (2 papers, 2021).
meningioma (2 papers, 2019 to 2023). A generally slow growing tumor attached to the dura mater. "Furthermore, of the four DREAM complex target genes shown to be upregulated in type C tumors, only PBK was higher in our NF2-2 meningiomas, while the expression of the 3 other genes (TTK, MELK, and CDK1) was not significantly different between the subgroups." (PMID 36937440, 2023).
mesothelioma (2 papers, 2022 to 2023). A usually malignant and aggressive neoplasm of the mesothelium which is often associated with exposure to asbestos. "Palbociclib led to a substantial loss of CDK1 gene expression in all three mesothelioma cell lines." (PMID 37298855, 2023). "The nanoconstruct targeted EGFR (a mesothelioma overexpression receptor), and the main targets were genes involved in the progression of this cancer, e.g., BCL2, CDK1, and JUN." (PMID 35326459, 2022).
osteoarthritis (2 papers, 2016 to 2021). A noninflammatory degenerative joint disease occurring chiefly in older persons, characterized by degeneration of the articular cartilage, hypertrophy of bone at the margins and changes in the synovial membrane. "Given the availability of inhibitors of Cdk1 activity, our results could provide insight for the treatment of diseases involving abnormal chondrocyte proliferation, such as osteoarthritis." (PMID 26860366, 2016). "Thus, Cdk1 could also be a potential therapeutic target for the treatment of bone and joint diseases such as osteoarthritis and osteochondrodysplasias by modulating chondrocyte proliferation and differentiation." (PMID 26860366, 2016).
papillary carcinoma (2 papers, 2021 to 2022). A malignant epithelial neoplasm characterized by a papillary growth pattern. "ERBB3/ERBB4/RAF1 kinases were activated in papillary carcinoma compared to other variants, PAK3/PAK6/CDK1 kinases were activated in NOS, and PRKACA/PRKACB/PRKACG kinases were activated in differentiation variants." (PMID 35659036, 2022).
synovial sarcoma (2 papers, 2019 to 2024). "Investigations into the molecular mechanisms underpinning FAM83D’s regulation of STAT1, BIRC5, MCM2, as well as CDK1 in synovial sarcoma, are currently underway in our laboratory." (PMID 38512482, 2024). "Collectively, these results point to a potential involvement for FAM83D in the development of synovial sarcoma could be mediated via the regulation of STAT1, BIRC5, MCM2, as well as CDK1." (PMID 38512482, 2024).
Transient cerebral ischemia (2 papers, 2018 to 2022). "Remarkably, the Ser1231 site is a multitarget residue that can be also phosphorylated by the extracellular signal-regulated kinase 1 and 2 (ERK1/2) —whose expression and activation are enhanced upon transient cerebral ischemia —and additionally, by the cyclin-dependent kinase 1 (Cdk1)." (PMID 35163752, 2022).
vitiligo (2 papers, 2021). Generalized well circumscribed patches of leukoderma that are generally distributed over symmetric body locations and is due to autoimmune destruction of melanocytes. "The hub genes of vitiligo melanocytes include CDK1, HSP90AA1, AKT1, BCL2L1, HDAC2, HELLS, and KIF23." (PMID 33790887, 2021). "These articulation proteins mainly included TXN (Thioredoxin), PBK, CDK1 (Cyclin-dependent kinase 1), which may be served as potential therapeutic targets for vitiligo." (PMID 34603063, 2021). "With the framework, we had successfully predicted and experimentally validated that some potential therapeutic targets such as CDK1 and PBK were closely related to melanogenesis, and further explored the multi-target strategy of kaempferide for vitiligo through proteomics profiling." (PMID 34603063, 2021).
vulvar cancer (2 papers, 2015 to 2018). "There was a clear downregulation of cell cycle regulators CDC25C, CDK1, and Cyclin A in both lines and cleavage of caspase 3, suggesting that CHK1 inhibition affects both proliferation and apoptosis of vulvar cancer cells." (PMID 29963769, 2018). "However, to our knowledge no previous study has investigated Cyclin B1 and CDK1 in vulvar cancer." (PMID 25849598, 2015).
abdominal aortic aneurysm (1 paper, 2019). Enlargement and ballooning of the vessel that supplies arterial blood to the abdomen, pelvis and legs. "Differential expression of the hub gene CDK1 between abdominal aortic aneurysm and TAD should also be verified." (PMID 31751374, 2019).
acute kidney injury (1 paper, 2025). Sudden and sustained deterioration of the kidney function characterized by decreased glomerular filtration rate, increased serum creatinine or oliguria. "Furthermore, this study is the first to identify CDK1 and STAT1 as independent risk factors for acute kidney injury in gastrointestinal cancer patients, positioning them as potential diagnostic biomarkers." (PMID 39911265, 2025).
adrenal cortical adenomas (1 paper, 2018). "We studied CDK1 protein expression by immunohistochemistry in additional independent samples [ACC (n=12), adrenal cortical adenomas (n=38)], and found that CDK1 expression was significantly higher in ACC (p<0.01)." (PMID 30250647, 2018). "In GSE12368 dataset, CDK1 and CDK2 mRNA expressions were significantly higher in ACC (n=12) compared to normal (n=6, p=0.02) and adrenal adenoma (n=16, p<0.01)." (PMID 30250647, 2018). "We confirmed this finding in an independent dataset (GSE33371) and found significantly higher CDK1 and CDK2 mRNA expressions in ACC (n=33) compared to normal (n=10, p<0.01) and adrenal adenoma (n=22, p<0.01)." (PMID 30250647, 2018).
adrenocortical tumors (1 paper, 2019). "Meanwhile, CDC2, sharing approximately 63% amino-acid homology with CDK1, was found to be dysregulated in the cell cycle or retinoic acid signaling pathway by meta-analysis of genomic profiling data of adrenocortical tumors." (PMID 31572440, 2019).
AIDS (1 paper, 2023). A syndrome resulting from the acquired deficiency of cellular immunity caused by the human immunodeficiency virus (HIV). "However, the association of CDK1 polymorphisms and HIV-1infection and AIDS progression remains unclear." (PMID 37468905, 2023).
aneuploidy (1 paper, 2023). Chromosomal disorder consisting of the presence a chromosomal abnormality in which there is an addition or loss of chromosomes within a set. "Thus, change in timing of meiosis reentry and altered CDK1 activation may be linked to the aneuploidy described in aged oocytes." (PMID 36697412, 2023).
basal cell carcinoma (1 paper, 2015). A carcinoma involving the basal cells. "Shh signaling, driven exclusively by PTCH1 that is SMO/GLI1-independent, includes induction of apoptosis in endothelial and neuroepithelial cells and regulation of the Cyclin B1/CDK1 pathway in basal cell carcinoma." (PMID 26545965, 2015).
brucellosis (1 paper, 2025). Brucellosis is a bacterial infection that spreads from animals to people via unpasteurized dairy products or by exposure to contaminated animal products or infected animals. "Importantly, through the analysis with GBM and Random Forest models, CDK1, MAPK11, and PDIA3 were further identified as potential diagnostic marker genes for brucellosis." (PMID 40996975, 2025). "The abnormal levels of CDK1, MAPK11, PDIA3, and immune cells in brucellosis may be involved in the disease’s pathogenic mechanisms." (PMID 40996975, 2025). "RT-qPCR validation confirmed that the mRNA levels of CDK1, MAPK11, and PDIA3 were significantly elevated in brucellosis patients compared to the control group." (PMID 40996975, 2025). "In the GSE69597 dataset, the expression levels of CDK1, MAPK11, and PDIA3 were significantly higher in patients with brucellosis compared to the control group." (PMID 40996975, 2025). "Similarly, Western blot experiments revealed that the protein expression levels of CDK1, MAPK11, and PDIA3 were significantly higher in patients with brucellosis than in the control group." (PMID 40996975, 2025).
cardiac hypertrophy (1 paper, 2024). "Additionally, cardiac hypertrophy was mitigated, and survival rates post-MI were increased in Cdk1-knockout mice." (PMID 39409153, 2024).
chondrosarcoma (1 paper, 2015). A malignant cartilaginous matrix-producing mesenchymal neoplasm arising from the bone and soft tissue. "Our results demonstrate for the first time that the SYSADOA diacerein decreased the viability of human chondrosarcoma cells and induces G2/M cell cycle arrest by CDK1/cyclin B1 down-regulation." (PMID 26555773, 2015). "Our results demonstrate for the first time that diacerein decreased the viability of human chondrosarcoma cells and induces G2/M cell cycle arrest by CDK1/cyclin B1 down-regulation." (PMID 26555773, 2015).
chordoma (1 paper, 2024). Chordomas are rare malignant tumors arising from embryonic remnants of the notochord in axial skeleton. "In this study, we determined the capability of the CDK7 inhibitor THZ1 and the CDK1/2/5/9 inhibitor dinaciclib to reduce TBXT expression at mRNA and protein levels in a broad range of nine cell lines that are models of primary, recurrent, and metastasised chordoma of the clivus and the sacrum." (PMID 38786326, 2024).
chronic myelomonocytic leukemia (1 paper, 2015). A myelodysplastic/myeloproliferative neoplasm which is characterized by persistent monocytosis, absence of a Philadelphia chromosome and BCR/ABL fusion gene, fewer than 20 percent blasts in the bone marrow and blood, myelodysplasia, and absence of PDGFRA or PDGFRB rearrangement. "It has been reported that CDK1 plays an important role in AML and in chronic myelomonocytic leukemia (CMML)." (PMID 25914884, 2015).
colorectal adenocarcinoma (1 paper, 2020). The most common type of colorectal carcinoma. "Altogether, the data show that colorectal adenocarcinoma HT-29 cells treated with OAT-449 exhibit classical signaling scenario of activation of Cdk1, NuMa, Histone H3 and Aurora B within 18 h." (PMID 32759730, 2020).
colorectal adenoma (1 paper, 2022). An adenoma that arises from the colon or rectum. "Consistently, transcriptome analysis results showed that the expression levels of CDK1 correlated well with those of WDR5 in colorectal adenomas (GSE8671)." (PMID 35371306, 2022).
cutaneous squamous cell carcinoma (1 paper, 2025). "Here, we found that KY19382 and KY19334 inhibited the manifestation of malignant phenotype by inhibiting the Wnt/β-catenin signaling of human cutaneous squamous cell carcinoma (cSCC) cells, which was associated with suppression of cyclin-dependent kinase 1 (CDK1) expression." (PMID 40887499, 2025).